WNT10B (Wnt family member 10B)
Diseases named in the same sentence as WNT10B in open-access papers (continued):
Sharing a sentence is not in itself a finding about the gene and the disease.
melanoma (7 papers, 2012 to 2026). A malignant, usually aggressive tumor composed of atypical, neoplastic melanocytes. "The Wnt pathway, specifically Wnt10b, is a major pathway associated with melanoma recurrence in older patients with tumor-positive SLNs." (PMID 33373316, 2020). "Indicating the wide range of functional effects of Wnts not only in early tumor development, data analysis of RNA samples obtained from melanoma patients with positive sentinel lymph nodes (SLNs) revealed that Wnt10b is associated with melanoma recurrence in older patients with tumor-positive SLNs." (PMID 38388496, 2024). "Transfection of melanoma cell lines with a pool of siRNAs against Wnt10b led to a reduction in Wnt10b mRNA expression of ~40% after 48 h." (PMID 38388496, 2024). "Our melanoma cell lines showed high Wnt10b mRNA expression, which indicates that these cell lines differ in terms of their mRNA expression patterns, which led to different effects." (PMID 38388496, 2024). "Immunohistochemical staining of Wnt10b in human skin, primary tumor tissue and metastatic tissue revealed increased staining in melanoma tissue compared to skin, which was consistent with our qRT‒PCR results on the mRNA expression levels." (PMID 38388496, 2024). "WNT10B expression is upregulated in skin squamous cell carcinomas and older recurrent melanoma patients with tumor-positive sentinel lymph nodes." (PMID 36814601, 2023). "In our study, we found that Wnt10b was upregulated in older melanoma patients who experience recurrence." (PMID 33373316, 2020). "To confirm the role of Porcn function in Evi regulation without manipulating Wnt expression, we monitored Evi in the colon cancer cell line HCT116, that depends on Wnt secretion and in the melanoma cell line A375, that expresses Wnt5A and Wnt10B endogenously." (PMID 29378775, 2018). "Together, these results strongly implicate WNT9A and WNT10B as candidates for regulating endogenous WNT/β-catenin signalling in these melanoma cells." (PMID 23129487, 2012). "Although we previously showed that Wnt6 reduces OIS in melanocytes but induces senescence in melanoma cell lines, we wanted to determine whether Wnt10b, which is also upregulated in melanoma cell lines, has a similar function." (PMID 38388496, 2024). "Furthermore, depletion of Wnt6, Wnt10b or β-catenin expression in melanoma cells resulted in the induction of senescence." (PMID 38388496, 2024). "Furthermore, the injection of WNT10B protein into the tumor (subcutaneous injection of B16F10 melanoma cells) in mice inhibited tumor growth." (PMID 36814601, 2023). "Although high levels of WNT2, WNT7B and WNT10B are reported to activate WNT/β-catenin signalling, several studies report a reduction in nuclear β-catenin staining in high-risk melanoma patients." (PMID 23129487, 2012). "In addition, Wnt10b is upregulated in mouse tumor models of melanoma." (PMID 36814601, 2023). "Incubation with just one Wnt ligand, either Wnt6 or Wnt10b, led to a disruption in the OIS of BRAFm-transduced melanocytes from OIS, whereas in melanoma cells, knockdown of the respective Wnt6 expression induced a senescent phenotype." (PMID 38388496, 2024). "Based on the effect of Wnt10b on OIS in melanocytes, we then investigated the function of Wnt10b in melanoma cell lines and determined the status of senescence after the knockdown of Wnt10b." (PMID 38388496, 2024). "It significantly reduced the transcript levels of LEF1, WNT10B, MITF-M, c-MYC and CCND1 and increased the mRNA levels of FZD7 and DKK1 in all melanoma cell populations." (PMID 27351373, 2016). "In contrast to an oncogenic role for WNT10B in melanoma described previously, in a mouse cell line model of melanoma (B16F10), WNT10B reduced melanoma cell proliferation, induced cellular senescence, and enhanced tyrosinase (a marker of differentiation) activity in vitro." (PMID 36814601, 2023).
endometrial cancer (6 papers, 1997 to 2023). Primary or metastatic malignant neoplasm involving the endometrium (mucous membrane that lines the endometrial cavity). "One group found that miR-148a is significantly downregulated in cancer-associated fibroblasts in endometrial carcinoma patients and that WNT10B was upregulated." (PMID 36814601, 2023). "WNT10A and WNT10B proteins have been implicated in estrogen-related carcinogenesis of endometrial cancer." (PMID 26366420, 2015). "In endometrial cancer stem cells, WNT10B activity is regulated by the matricellular glycoprotein SPARC-related modular calcium binding 2 (SMOC-2)." (PMID 36814601, 2023). "Similar to the findings for WNT-7, the expression levels of WNT-10B were significantly higher in endometrial cancer tissue than in the normal endometrium." (PMID 37176048, 2023). "In comparison, in vitro cell studies show that the proliferation of Ishikawa 3-H-12 and AN3CA endometrial carcinoma cell lines was higher when WNT10B was overexpressed relative to control." (PMID 36814601, 2023). "miR-148a, the most studied of the RNAs, regulates WNT10B in adipocytes, lung fibrosis, pancreatic cancer, oral squamous cell carcinoma, colon adenocarcinoma, endometrial carcinoma, and thyroid cancer." (PMID 36814601, 2023). "By immunohistochemistry of the proliferative phase, secretory phase, simple hyperplasia, complex hyperplasia, atypical hyperplasia, and endometrial carcinoma tissues, WNT10B had increased expression in the cancerous endometrial carcinoma samples." (PMID 36814601, 2023). "Wnt10b protein expression is significantly higher in endometrial cancer tissue in comparison to hyperplastic endometrium and normal endometrium." (PMID 34068065, 2021). "The amount of WNT10B protein was higher in endometrial cancer than in hyperplastic and normal endometrium as determined by Western blot technique." (PMID 26366420, 2015). "In fresh tissues, all Wnt genes apart from Wnt10b were expressed in normal endometrium and endometrial carcinoma." (PMID 9099960, 1997). "Furthermore, they demonstrated that WNT10B is directly responsible for the increase in tumor cell motility in endometrial cancer cells." (PMID 36814601, 2023). "Two studies have shown post-transcriptional regulation of WNT10B in endometrial cancer." (PMID 36814601, 2023). "In early stages of endometrial cancer, the expression of WNT10B was higher than in later stages." (PMID 26366420, 2015).
Oligodontia (6 papers, 2018 to 2023). The absence of six or more teeth from the normal series by a failure to develop. "Four different coding mutations in WNT10B (p.Arg211Gln, p.Pro190Arg, p.Trp262∗, and p.Phe284Cys) have been detected in families with oligodontia." (PMID 36814601, 2023). "The mutations in WNT10B in Chinese families affect the development of permanent dentition and result in oligodontia, by attenuated Wnt signaling in endothelial differentiation of dental pulp stem cells." (PMID 30683673, 2019). "Mutations in numerous genes including msh homeobox 1 (MSX1), paired box 9 (PAX9), Wnt family member 10A (WNT10A), axis inhibition protein 2 (AXIN2), ectodysplasin A (EDA), and Wnt family member 10B (WNT10B) have been associated with nonsyndromic oligodontia." (PMID 30134957, 2018).
prostate carcinoma (6 papers, 2021 to 2023). A carcinoma that arises from epithelial cells of the prostate gland. "The endocrine-disrupting chemicals 17β-estradiol-3-benzoate (EB) and bisphenol A (BPA), which increase susceptibility to prostate cancer, decreased the DNA methylation of Wnt10b and subsequently increased the expression of Wnt10b in young rats." (PMID 36814601, 2023). "Overall, WNT10B’s mechanism in prostate cancer, particularly in cancer stem cell population, requires further study." (PMID 36814601, 2023). "Then, they examined the Probasin/TAg prostate cancer rat model and found that prostate cancer had a significantly decreased expression of Wnt10b compared to normal prostate tissue." (PMID 36814601, 2023). "Prostate cancer cells (PC-3) stimulated by Wnt ligands (Wnt5A, Wnt10B) were analyzed by Cy3-PLA for the co-localization of FZD6 and co-receptors (canonical: LRP6, non-canonical: ROR1) at the single-cell level." (PMID 34769487, 2021). "Oncogenic functions of WNT10B have been studied also in prostate cancer and they might be disease stage specific." (PMID 36809527, 2023). "WNT7B, WNT9A and WNT10B did indeed cause a small increase in LNCaP cell growth and motility, and WNT7B has been shown to be required for the growth of both androgen-dependent and castration-resistant prostate cancer cells in other studies." (PMID 37373067, 2023). "In the present report, we established a proximity ligation assay (PLA) to detect and quantify the co-localization of FZD6 with the major canonical co-receptor LRP6 as an early event of the well-documented Wnt/β-catenin signal transduction after Wnt10B stimulation in PC-3 prostate cancer cells." (PMID 34769487, 2021). "In the prostate cancer cell line PC3, WNT10B was shown by proximal ligation assay (PLA) to co-localize with FZD6 and LRP6 and then induce nuclear β-catenin in 5 min." (PMID 36814601, 2023). "For instance, overexpression of phb in human prostate cancer cells decreases the expression of several members of WNT family and reduces the motility and invasiveness of cancer cells, and phb plays an important role in the inter-regulation of wnt7b, wnt9a, and wnt10b with the cell cycle." (PMID 37868974, 2023).
tooth agenesis (6 papers, 2020 to 2023). A tooth disease characterized by failure to develop one or more missing teeth. "Research has identified an association between mutations in MSX1, PAX9, EDA, AXIN2, WNT10A, WNT10B and LRP6 and human tooth agenesis." (PMID 31914153, 2020).
acute myeloid leukaemia (4 papers, 2016 to 2023). "WNT10B is associated with multiple cancers and an intronless variant has been found in acute myeloid leukaemia, but the gene has not yet shown involvement in lymphoma." (PMID 37756103, 2023). "Defects in the control of Wnt signaling have emerged as a recurrent mechanism involved in cancer pathogenesis and acute myeloid leukaemia (AML), including the hematopoietic regeneration-associated WNT10B in AC133bright leukaemia cells, although the existence of a specific mechanism remains unproven." (PMID 27853307, 2016).
Osteopenia (4 papers, 2010 to 2022). Osteopenia is a term to define bone density that is not normal but also not as low as osteoporosis. "In conclusion we have demonstrated that loss of Wnt10b in mice results in an age-progressive osteopenia and that loss of one allele results in a fully penetrant osteopenic phenotype by 6 months of age." (PMID 20499361, 2010). "Here we show that Wnt10b-null mice have a progressive osteopenia resulting from defects in postnatal bone homeostasis." (PMID 20499361, 2010). "Interestingly, we found that Wnt10b-null animals showed enhanced trabecular structure at 2 and 4 weeks of age but that the increase was rapidly followed by progressive osteopenia from 2 to 6 months of age." (PMID 20499361, 2010).
osteosarcoma (4 papers, 2013 to 2024). A usually aggressive malignant bone-forming mesenchymal neoplasm, predominantly affecting adolescents and young adults. "However, WNT10B has been further implicated in osteosarcoma tumorigenesis and metastasis." (PMID 36814601, 2023). "We identified osteoblast differentiation genes (SP7 (osterix), ALPL, BMP4, and PHOSPHO1) in RNA-sequencing of osteosarcoma patient tumors and WNT10B correlated positively with these genes, while these genes inversely correlated with WNT5B." (PMID 39102216, 2024). "When WNT10B is highly expressed in osteosarcomas there is a correlation with worse survival outcomes." (PMID 39102216, 2024). "In comparison, WNT10B regulates osteoblastic differentiation and is more expressed in the osteoblastic subtype of osteosarcoma." (PMID 39102216, 2024). "Not only does WNT10B regulate normal bone, but WNT10B expression correlates with worse overall survival in osteosarcoma patients." (PMID 36814601, 2023). "In osteosarcoma, WNT10B expression is regulated by the transcriptional co-factor FHL2 (four and a half LIM domains protein 2)." (PMID 36814601, 2023). "In all three metastatic lines, there was a significant upregulation of WNT10B, suggesting the role of WNT10B in osteosarcoma metastasis." (PMID 36814601, 2023). "FHL2 silencing also decreased the expression of c-Myc, which is involved in cell proliferation, and Wnt5a and Wnt10b, which are involved in osteosarcoma severity and invasiveness." (PMID 23383046, 2013). "Research to determine the mechanism by which WNT10B could be affecting osteosarcoma is limited." (PMID 36814601, 2023). "In contrast, MG-63 cells (another osteosarcoma cell line) had no detectable expression of WNT10B mRNA, similar to either MCF-7 (ER+) and MCF-10A (a TNBC control “normal” cell line), and MG-63 cells responded robustly to JA exposure as compared to U2OS cells." (PMID 29281678, 2017). "In murine osteosarcoma cells, FHL2 silencing using shRNA decreased canonical Wnt/β-catenin signaling and reduced the expression of Wnt responsive genes as well as of the key Wnt molecules Wnt5a and Wnt10b." (PMID 23383046, 2013). "The mechanism of WNT10B in osteosarcomas has not been elucidated." (PMID 39102216, 2024). "Furthermore, WNT10B and WNT5B regulate different histological subtypes of osteosarcomas." (PMID 39102216, 2024). "Jude Children’s Research Hospital (p < 0.05, data not shown), and 23 osteosarcoma tumors from GEO dataset GSE36004 (p < 0.02, data not shown) revealed that WNT5B and WNT10B are not expressed in the same tumors." (PMID 39102216, 2024). "WNT5B, a β-catenin-independent ligand, and WNT10B, a β-catenin-dependent WNT ligand, are each expressed in osteosarcomas, but they are not expressed in the same tumors." (PMID 39102216, 2024).
pancreatic cancer (4 papers, 2019 to 2024). "Activation of Wnt10B/β-catenin axis was significantly associated with poor survival of patients with pancreatic cancer." (PMID 31528218, 2019). "MiR-148a also suppresses the invasion and metastasis of pancreatic cancer by targeting Wnt10b and WNT signaling paths." (PMID 38559560, 2024). "At the time of our previous review, the only mention of WNT10B in pancreatic cancer was at the expression level." (PMID 36814601, 2023). "In pancreatic cancer, Wnt10B, combined with β-catenin, enhanced the EMT and contributed to cancer dissemination." (PMID 31528218, 2019). "miR-148a inhibits WNT10B not only in pancreatic cancer, but also in thyroid cancer." (PMID 36814601, 2023). "Each of the fatty acid synthase/Wnt, miR-148a/Wnt10b, Linc00261/miR-552-5p/FOXO3, and miR-454/FAM83A/TSPAN1 axes can be valuable biomarkers and potential therapeutic targets in pancreatic cancer." (PMID 38559560, 2024).
chronic kidney disease (3 papers, 2020 to 2024). Impairment of the renal function secondary to chronic kidney damage persisting for three or more months. "Wnt10b has been shown to be a potential novel therapeutic target for postmenopausal osteoporosis and chronic kidney disease (CKD) related skeletal diseases." (PMID 39188952, 2024). "Moreover, researchers have suggested that cinacalcet, probably via increased bone mineralization related to osteoclastic Wnt10b secretion, might improve bone quantity, and quality in chronic kidney disease (CKD) mice." (PMID 33013696, 2020).
glioma (3 papers, 2020 to 2023). A benign or malignant brain and spinal cord tumor that arises from glial cells (astrocytes, oligodendrocytes, ependymal cells). "Our results indicated that mRNA expressions of WNT5A and WNT10B were significantly differentially regulated in glioma compared with NB tissues, and associated with pathology and grade of glioma." (PMID 32181818, 2020). "Furthermore, the expression of WNT5A and WNT10B was associated with the clinicopathology of glioma." (PMID 32181818, 2020). "In glioma-derived U-87MG cells, shFABP4 significantly reduced the expression of WNT10B by immunofluorescence and RT-qPCR." (PMID 36814601, 2023). "On the other hand, though we performed analysis to predict the mechanism and biofunction of WNT5A and WNT10B in glioma, a remarkable amount of work is urgent to investigate the distinct role of WNTs in glioma." (PMID 32181818, 2020). "For CNS tumor, higher expression of WNT5A, lower expression of WNT7A and lower expression of WNT10B were found in glioma compared with NB tissues." (PMID 32181818, 2020). "To understand the function and molecular mechanism of WNT5A and WNT10B in glioma, we performed PPI network, GO and KEGG analyses." (PMID 32181818, 2020). "Although our study provided important insights into the prognostic and research values of WNT5A and WNT10B in glioma patients at the mRNA level, there still are some limitations to the present study." (PMID 32181818, 2020). "For WNT10B, in contrast with the results of WNT5B, significant lower mRNA expression of WNT10B in glioma was observed compared with NB." (PMID 32181818, 2020). "Conversely, the increased mRNA expression levels of WNT3, WNT5B and WNT10B were correlated with better OS in patients with glioma." (PMID 32181818, 2020). "The GO enrichment analysis was then performed to determine the function of WNT5A and WNT10B with neighbor genes in glioma using DAVID." (PMID 32181818, 2020). "The study also indicated that WNT5A can serve as a candidate to diagnose and therapy glioma, while WNT10B might be valuable for anti-glioma research." (PMID 32181818, 2020). "Analyzing the mRNA data of 19 WNTs from TCGA and CGGA database, we found that WNT5A mRNA expression level was significantly correlated with the grade of glioma in both TCGA and CGGA databases; however, WNT10B expression was inversely correlated with the grade of glioma." (PMID 32181818, 2020). "Furthermore, we verified that the mRNA expression of WNT10B was inversely proportional to the WHO grade of glioma." (PMID 32181818, 2020). "Despite the down-regulation of WNT10B expression in glioma, the most important molecule in the classical pathway, β-catenin is up-regulated in glioma and also reported accumulation in the nucleus of glioma." (PMID 32181818, 2020). "In addition, WNT5A was positively correlated and WNT10B inversely correlated with glioma grade." (PMID 36814601, 2023). "In addition, GO analysis predicted that WNT10B regulated molecular functions including GTPase activity, biological processes such as signal translation, and biological pathways such as development biology in glioma." (PMID 32181818, 2020). "According to our study, we suggested a new point that WNT10B might function as a glioma suppressor." (PMID 32181818, 2020). "A bioinformatics analysis of all 19 WNT ligands in human gliomas revealed an overexpression of WNT5A and a decreased expression of WNT10B in tumors compared to normal tissue." (PMID 36814601, 2023). "WNT5A played role in glioma by taking part in WNT/Ca2+pathway and the canonical pathway, however, WNT10B was only ligands of canonical pathway." (PMID 32181818, 2020). "Furthermore, the overexpression of WNT5A and WNT16 correlated with worse overall survival in glioma patients, whereas high expression of WNT5B, WNT10B, and WNT3 correlated with better overall survival probability." (PMID 36814601, 2023).
glioma (continued). "As WNT5A and WNT10B were the most correlated with glioma prognosis and clinicopathology, we analyzed the 50 most frequently altered neighbor genes of WNT5A and WNT10B in glioma and constructed integrated networks using String." (PMID 32181818, 2020).